RNU1-2 (RNA, U1 small nuclear 2)
Synonyms: U1C1; U1C21; RNU1C1; RNU1C2
Gene: Small nuclear RNA gene on chromosome 1 (16,895,980 to 16,896,143, forward strand). Ensembl gene ENSG00000207005.
Gene Ontology:
Molecular function: pre-mRNA 5'-splice site binding
Biological process: mRNA 5'-splice site recognition
Cellular component: U1 snRNP
Homologues: Orthologues: dog U1 (100% identical), guinea pig U1 (100% identical), macaque U1 (100% identical), pig U1 (100% identical), dog U1 (88% identical). Paralogues in human: RNU1-1 (100% identical), RNU1-27P (100% identical), RNU1-28P (100% identical), RNU1-3 (100% identical), RNU1-4 (100% identical), RNVU1-18 (100% identical), RNVU1-29 (100% identical), U1 (100% identical), RNVU1-28 (99% identical), RNVU1-7 (99% identical), RNVU1-31 (99% identical), RNU1-89P (97% identical), and 134 more.
Diseases named in the same sentence as RNU1-2 in open-access papers:
RNU1-2 is named in the same sentence as 9 diseases in open-access papers, as found by Europe PMC text mining. Sharing a sentence is not in itself a finding about the gene and the disease. The quoted sentences say what the papers report.
cerebellar ataxia (4 papers, 2020 to 2022). A neurological syndrome characterized by clumsy and uncoordinated movement of the limbs, trunk, and cranial muscles. "Recently, an 84C>T mutation in the U12 snRNA gene (RNU12) has been shown to cause an early-onset form of cerebellar ataxia (EOCA) with autosomal recessive inheritance." (PMID 33577674, 2021). "In this study, we have investigated the molecular mechanism underlying Early onset cerebellar ataxia caused by the 84C>T mutation in the RNU12 gene encoding U12 snRNA, a component of the minor spliceosome." (PMID 33577674, 2021). "Nevertheless, CAs caused by variants in non-coding DNA sequences have also been reported, like early-onset cerebellar ataxia associated with non-coding RNA, RNU12." (PMID 34224032, 2021). "RNU12 biallelic variants have been found so far in a single large consanguineous family in which members displayed autosomal recessively inherited early onset cerebellar ataxia, while RNU4ATAC biallelic variants have been reported in 46 families to date." (PMID 32628740, 2020).
gastric cancer (1 paper, 2023). A primary or metastatic malignant neoplasm involving the stomach. "This study revealed the gastric cancer-associated lncRNA RNU12 is a tumor-suppressor lncRNA that inhibits cancer progression via miR-575/BLID axis, which plays crucial role in gastric cancer progression and suggest that RNU12 is potential GC marker and target for GC therapy." (PMID 37160927, 2023). "qRT-PCR was utilized for determining the RNU12 expression in cell lines, 113 cases of paired gastric cancer (GC) and their adjacent normal gastric tissues." (PMID 37160927, 2023).
lymph node metastasis (1 paper, 2023). "The clinical data demonstrated a negative relationship between RNU12 expression and clinic pathologic feature-lymph node metastasis in GC patients (P < 0.05)." (PMID 37160927, 2023).
tumor (1 paper, 2023). "The GC tumor xenograft in zebrafish model was used for exploring the association of the RNU12 biological function in vivo." (PMID 37160927, 2023). "Our previous results have discovered that RNU12 was a decreased expression level in GC, suggesting that RNU12 is an essential regulator in suppressing tumor genesis." (PMID 37160927, 2023). "Our present data supported the function of RNU12 in inhabiting GC tumor progression through suppressing the cell growth, migration, invasion, as well as the proliferative ability expression with CCND1, PCNA, N-cadherin, E-cadherin, Vimentin and BCL-2." (PMID 37160927, 2023). "Here, we explored the function of RNU12 in controlling the tumor growth and progression and found that RNU12, as a sponge of miR-575, reduced miR-575 expression, regulated BLID expression and reduced GC cell proliferation and metastasis." (PMID 37160927, 2023). "RNU12 is one of long noncoding RNAs (lncRNAs) regulating the tumor progression." (PMID 37160927, 2023).
RNU1-2 also shares sentences with these, for which no sentence is quoted: cancer (1 paper); craniosynostosis (1); Macrocephaly (1); neurodegenerative disease (1); Obesity (1).